RGS6 (regulator of G protein signaling 6)
Description:
Regulates G protein-coupled receptor signaling cascades. Inhibits signal transduction by increasing the GTPase activity of G protein alpha subunits, thereby driving them into their inactive GDP-bound form. The RGS6/GNB5 dimer enhances GNAO1 GTPase activity.
Synonyms: GAP; HA117; S914
Tractability: Antibody: UniProt places it where antibodies can reach, with high confidence; its Gene Ontology location is reachable by antibodies, with high confidence. PROTAC: its protein half-life has been measured.
Gene: Protein-coding gene on chromosome 14 (71,932,429 to 72,566,530, forward strand). Ensembl gene ENSG00000182732.
Subcellular location: Cytoplasm; Cytoplasm, cytosol; Membrane; Nucleus; Cell membrane
Subcellular location (Human Protein Atlas): Nucleoplasm; Nucleoli; Vesicles
Pathways (Reactome):
Metabolism of proteins: Cooperation of PDCL (PhLP1) and TRiC/CCT in G-protein beta folding
Signal Transduction: G alpha (i) signalling events
Gene Ontology:
Molecular function: GTPase activator activity; protein binding; GTPase activity
Biological process: positive regulation of GTPase activity; G protein-coupled receptor signaling pathway; regulation of G protein-coupled receptor signaling pathway; intracellular signal transduction
Cellular component: cytoplasm; cytosol; membrane; nucleoplasm; nucleus; neuron projection; plasma membrane
Genetic constraint (gnomAD): Loss-of-function variants: 23 observed, 49.09 expected, observed/expected ratio (o/e) 0.47, 90% interval 0.34 to 0.66. The upper end of that interval is the gene's LOEUF score, 0.66, which puts it in group 2 of 6, group 1 being the genes least tolerant of losing a copy. Missense variants: 372 observed, 481.71 expected, observed/expected ratio (o/e) 0.77, 90% interval 0.71 to 0.84. Synonymous variants: 165 observed, 170.82 expected, observed/expected ratio (o/e) 0.97, 90% interval 0.85 to 1.1.
Homologues: Orthologues: guinea pig RGS6 (98% identical), mouse Rgs6 (98% identical), rat Rgs6 (96% identical), macaque RGS6 (90% identical), pig RGS6 (89% identical), rabbit RGS6 (88% identical), tropical clawed frog rgs6 (88% identical), chimpanzee RGS6 (84% identical), dog RGS6 (84% identical), zebrafish rgs6 (82% identical). Paralogues in human: RGS7 (71% identical), RGS9 (37% identical), RGS11 (33% identical), RGS3 (20% identical), RGS22 (20% identical), RGS12 (19% identical), RGSL1 (19% identical), RGS14 (13% identical), AXIN1 (13% identical), RGS17 (12% identical), RGS1 (12% identical), RGS20 (12% identical), and 11 more.
Diseases named in the same sentence as RGS6 in open-access papers:
RGS6 is named in the same sentence as 54 diseases in open-access papers, as found by Europe PMC text mining. Sharing a sentence is not in itself a finding about the gene and the disease. The quoted sentences say what the papers report.
schizophrenia (6 papers, 2019 to 2025). A major psychotic disorder characterized by abnormalities in the perception or expression of reality. "Consistent with this, a SNP (single nucleotide polymorphism) (rs2332700) in regulator of G-protein signaling 6 (RGS6) is linked to autism spectrum disorder, bipolar disorder, major depression, and schizophrenia." (PMID 34880111, 2022). "Two differentially expressed genes associated with schizophrenia, RGS6 and PTPRK, are detected within the exc-a subcluster and are recognized as high-confidence susceptibility genes for schizophrenia." (PMID 39397771, 2025). "One of the most important molecules in the central nervous system is ‘RGS6’, which is found in a lot of psychiatric disorders like depression and schizophrenia." (PMID 37494308, 2023). "Moreover, linkage studies in humans with RGS6, 7, 8, 5, 19, and 12 implicate their involvement in anxiety, depression, bipolar disorders, and/or schizophrenia." (PMID 31633064, 2019). "Comparison of differential transcriptomic profiles and GWAS/WGS profiles identified 3 significant shared genes (ETS1, RGS6, BRINP2) commonly present between obesity and schizophrenia pair in both analyses." (PMID 37494308, 2023). "Possibly, new genes (RGS6 and PTPRK) have been identified in an excitatory neuronal subpopulation that might be important in the pathophysiology of schizophrenia." (PMID 39397771, 2025).
bladder cancer (5 papers, 2016 to 2024). "RGS proteins were first found to be associated with cancer in 2004, when it was discovered that a single nucleotide polymorphism (SNP) in the RGS6 gene (rs2074647) was positively correlated with a decreased risk of bladder cancer, particularly in smokers." (PMID 37118788, 2023). "A role of RGS6 in preventing tumorigenesis was first suggested by a finding that a single nucleotide polymorphism (SNP), which increases RGS6 gene expression up to 3 folds, is correlated with low risk of developing bladder cancer." (PMID 35902557, 2022). "Given that an activating SNP in the human RGS6 gene is associated with a reduced risk of bladder cancer, we examined the possibility that RGS6 functions as a tumor suppressor by examining its expression in UBC." (PMID 27713144, 2016). "A SNP in the RGS6 gene, which increases RGS6 expression, is associated with a significant reduction in the risk of human bladder cancer." (PMID 27713144, 2016). "In particular, this polymorphism in RGS6 was associated with a 34% reduction in bladder cancer incidence with stratified analyses revealing a 40% and 58% cancer reduction in smokers and in those who began smoking at young age, respectively." (PMID 27713144, 2016). "However, in BBN-fed mice, RGS6 loss was associated with a significant acceleration in bladder cancer progression." (PMID 27713144, 2016). "Regulator of G-protein signaling 6 (RGS6) is a newly discovered tumor suppressor that has been shown to be protective in development of various cancers such as breast cancer and bladder cancer." (PMID 35902557, 2022). "Previous studies had explored the associations between RGS family members and bladder cancer risk, including RGS1, RGS2, RGS4, RGS5, RGS6, and RGS20." (PMID 34482807, 2021). "The striking loss of RGS6 in human UBC, together with our finding that an activating SNP in RGS6 is associated with a reduced risk of bladder cancer, strongly support the tumor suppressor role of RGS6 described here." (PMID 27713144, 2016). "Significantly, abnormal expression of multiple RGS proteins, such as RGS17 in hepatocellular carcinoma, lung cancer, and prostate cancer, RGS5 in ovarian cancer and squamous cell carcinoma, and RGS6 in breast cancer and urinary bladder cancer, has been documented in relation to tumor progression." (PMID 38906869, 2024). "Moreover, downregulation of RGS6 expression has been found in various cancer tissues, including breast cancer, bladder cancer, colorectal cancer and pancreatic cancer." (PMID 35902557, 2022).
breast carcinoma (5 papers, 2018 to 2024). "RGS2, RGS4 and RGS6 repress cell growth, whose expression is decreased in breast cancer cells, compared to the normal cells." (PMID 37118788, 2023). "For example, some RGS proteins including RGS4, RGS16, RGS2, RGS6 and RGS17 negatively regulate the progression of breast cancer, whereas RGS20 protein exerts the positive effects on potentiating the carcinogenesis of breast cancer." (PMID 37118788, 2023).
depression (5 papers, 2019 to 2024). "As related to depression, the RGS family members, RGS2, RGS4, RGS6 and RGS8 have all surfaced as being involved with regulating the manifestation of depression or play role as antidepressants through their capacity to activate different downstream molecular mechanisms." (PMID 34674723, 2021).
Obesity (5 papers, 2011 to 2025). Accumulation of substantial excess body fat. "Another GWAS found that the genes FBN2, LINC01122, and RGS6, which relate to obesity, are also linked to sleep activity in children." (PMID 40024983, 2025). "Associations of RGS6 gene variants with obesity-related index: multivariate linear regression analysis." (PMID 26340433, 2015). "Human genetic studies have linked variations in two other R7 RGS proteins, RGS6 and RGS7 to obesity." (PMID 22132185, 2011). "Another gene regulating arabinonic acid, RGS6, belongs to the RGS (G protein signaling regulator) protein family and is associated with GTPase activator activity, which plays a significant role in obesity and cardiovascular disease." (PMID 40429682, 2025).
Parkinson disease (5 papers, 2014 to 2025). A progressive degenerative disorder of the central nervous system characterized by loss of dopamine producing neurons in the substantia nigra and the presence of Lewy bodies in the substantia nigra and locus coeruleus. "A number of RGS family proteins have been implicated in the development of Parkinson’s Disease including a study of RGS6 in which expression of RGS6 in substantia nigra pars compacta dopaminergic neurons suppressed Parkinson’s Disease phenotypes in aged mice." (PMID 41271702, 2025). "While the loss of Rgs6 function may predispose or contribute to Parkinson disease, its stimulation may provide a novel therapeutic avenue to treat Parkinson disease." (PMID 25501001, 2014). "In human dopamine neurons, the expression of RGS6 is restricted but can regulate the D2R-Gi/o pathway and can prevent Parkinson’s neurodegeneration, resulting in the accumulation of α-neurite nuclein." (PMID 35309141, 2022).
Anxiety (4 papers, 2014 to 2024). Intense feelings of nervousness, tension, or panic often arise in response to interpersonal stresses. "In this study, the endogenous regulator of G-protein signaling 6 (RGS6) implicated as inhibitor of 5-HT1a receptors, was knocked out which resulted in anxiety and pCREB level alterations." (PMID 25505876, 2014).
atrial fibrillation (4 papers, 2013 to 2021). A disorder characterized by an electrocardiographic finding of a supraventricular arrhythmia characterized by the replacement of consistent P waves by rapid oscillations or fibrillatory waves that vary in size, shape and timing and are accompanied by an irregular ventricular response. "Decreased RGS6 caused irregular cardiac rhythmicity and raised susceptibility to atrial fibrillation, which was contributed by m2R-IKACh intracellular signaling pathway." (PMID 33892733, 2021). "Ablation of the major regulator of this pathway, Rgs6, in mice results in irregular cardiac rhythmicity and increases susceptibility to atrial fibrillation." (PMID 24204714, 2013). "We next asked whether increased HRV in Rgs6−/− mice predisposes or protects mice to/from atrial fibrillation (AF)." (PMID 24204714, 2013). "Loss of Rgs6 in mice and disruption of orthologous gene product in humans lead to increased HRV and susceptibility to atrial fibrillation." (PMID 24204714, 2013).
lung carcinoma (4 papers, 2022 to 2024). "Interestingly, some of the literatures reported low expression of RGS6 was associated with poor survival in lung cancer patients." (PMID 38066447, 2023). "An epidemiological study linking PDZ-RhoGEF polymorphisms with lung cancer risk suggested that there were interactions between RGS2, RGS6, and PDZ-RhoGEF and validated this family of proteins as key regulators of tumorigenesis." (PMID 38066447, 2023). "Low level of RGS6 is more prominent in metastatic lung cancer tissues and correlated with poor prognosis of lung cancer patients." (PMID 35902557, 2022). "In summary, this work demonstrates a novel function of RGS6 in formation and metastasis of lung cancer." (PMID 35902557, 2022). "Here, we first investigated the function of RGS6 in lung cancer development and particularly, in cancer metastasis." (PMID 35902557, 2022). "Collectively, our data showed that RGS6 expression was downregulated in lung cancer tissues, especially in metastatic lung cancer tissues, and low RGS6 expression was associated with poor survival in LUAD patients, suggesting that RGS6 may play a role in suppressing NSCLC metastasis." (PMID 35902557, 2022). "Both RGS6 mRNA and protein levels are downregulated in human lung cancer tissues compared to noncancerous counterparts." (PMID 35902557, 2022). "To validate the clinical significance of these data, we next examined RGS6 mRNA levels in 92 human lung cancer tissues (including 78 NSCLC cases) and paired adjacent noncancerous tissues." (PMID 35902557, 2022). "Using both bioinformatics and experimental tools, we showed that RGS6 was downregulated in lung cancer tissues compared to noncancerous counterparts, and low expression of RGS6 was associated with poor survival of lung cancer patients." (PMID 35902557, 2022).
ovarian carcinoma (3 papers, 2022 to 2024). A malignant neoplasm originating from the surface ovarian epithelium. "However, RGS6 expression has been found to be greatly upregulated in certain types of ovarian cancer cell lines." (PMID 35902557, 2022).
Arrhythmia (2 papers, 2013 to 2018). Any cardiac rhythm other than the normal sinus rhythm. "In addition, Girk4-/- mice were resistant to the onset of arrhythmias post injection of CCh, as opposed to both Rgs6-/- and WT mice." (PMID 29668674, 2018).
Ataxia (2 papers, 2015 to 2023). Ataxia refers to impaired coordination of voluntary muscle movement. "Mice lacking RGS6 exhibited abnormal gait and ataxia characterized by impaired rotarod performance." (PMID 38066447, 2023). "Mice lacking Rgs6 or Rgs9 exhibit motor function deficits and ataxia." (PMID 25902068, 2015).
Bradycardia (2 papers, 2018 to 2020). A slower than normal heart rate (in adults, slower than 60 beats per minute). "In line with its role as a negative regulator of atrial M2R-IKACh signaling, loss of RGS6 correlated with a mild resting bradycardia, enhanced HR and HRV responses to CCh, and increased propensity for arrhythmic episodes." (PMID 29668674, 2018). "Rgs6-/- mice displayed significantly lower baseline HR as well as exaggerated responses to CCh-induced bradycardia and increases in HRV, all of which have been previously reported." (PMID 29668674, 2018).
heart failure (2 papers, 2024 to 2025). Inability of the heart to pump blood at an adequate rate to meet tissue metabolic requirements. "Interestingly, and relevant to DCM pathogenesis, Rgs6−/− mice were protected against anthracycline (doxorubicin)-induced DCM leading to heart failure." (PMID 39772618, 2025). "Given that loss of functional myocytes and the resultant pathogenic remodeling represent a primary contributor to eventual heart failure, our data point to a key role for RGS6 in the pathogenesis of heart disease, which remains the leading cause of death in both men and women worldwide." (PMID 38409136, 2024). "Doxorubicin also increased expression of hypertrophy and heart failure markers β-MHC, atrial natriuretic peptide (ANP), and troponin T as well as the oxidative stress marker MDA via a RGS6-dependent mechanism." (PMID 38409136, 2024). "Whether the cardioprotective effect of RGS6 in DCM and heart failure is inherent in the RGS domain that executes GAP activity, or in other domains of the protein, remains to be elucidated." (PMID 39772618, 2025).
non-small cell lung carcinoma (2 papers, 2022 to 2023). A group of at least three distinct histological types of lung cancer, including non-small cell squamous cell carcinoma, adenocarcinoma, and large cell carcinoma. "In the respiratory system, RGS6 was found to suppress TGF-β-induced epithelial–mesenchymal transition in vitro, and TGF-β was found to promote metastasis in vivo through canonical TGF-β-SMAD signaling in non-small cell lung cancer (NSCLC)." (PMID 38066447, 2023).
nonalcoholic fatty liver disease (2 papers, 2023). "RGS6 was also found to be upregulated in the livers of patients with nonalcoholic fatty liver disease." (PMID 38066447, 2023). "A study confirmed that hepatic RGS6 increases oxidative stress and inflammation, which drive lipid deposition, fibrosis, and nonalcoholic fatty liver disease." (PMID 37033223, 2023).
Abdominal obesity (1 paper, 2023). Excessive fat around the stomach and abdomen. "Transcriptomic factor ‘RGS6’ are in charge of unusual food consumption and abdominal obesity in response to psychological and social strain." (PMID 37494308, 2023).
alcohol dependence (1 paper, 2022). Physical and psychological dependence on alcohol. "For example, studies reported that RGS6 abnormalities may be related to diseases, such as alcohol dependence, Parkinson’s syndrome, and neurological or affective disorders." (PMID 35309141, 2022).
bladder (1 paper, 2016). "RGS6 loss dramatically accelerates BBN-induced bladder carcinogenesis, with RGS6−/− mice consistently displaying more advanced pathological lesions than RGS6+/+ mice." (PMID 27713144, 2016).
bladder tumors (1 paper, 2016). "Therefore, BBN-induced upregulation of Ras in the bladder wall likely does not contribute to the increased incidence of bladder tumors in RGS6−/− mice." (PMID 27713144, 2016).
carcinoma in situ (1 paper, 2016). "In addition, while 100% of RGS6−/− mice displayed carcinoma in situ by 12 wks of BBN treatment, only 33% of RGS6+/+ had lesions at that time." (PMID 27713144, 2016).
cardiomyopathy (1 paper, 2025). A disease of the heart muscle or myocardium proper. "Based on the data showing that the absence of RGS6 decreased doxorubicin-induced myocardial cell apoptosis, the authors of that study concluded that RGS6 promotes doxorubicin-induced cardiomyopathy." (PMID 39772618, 2025).
chronic lung disease (1 paper, 2017). According to the definitions of the American and British Thoracic Societies, including pulmonary functional tests, X-rays, and CT scans for items such as fibrosis, bronchiectasis, bullae, emphysema, nodular or lymphomatous abnormalities. "Variants in FAM13A, as well as PARK2 and RGS6, have been associated with chronic lung disease in prior genome-wide association studies (GWAS)." (PMID 28178938, 2017).
Hepatic steatosis (1 paper, 2023). Steatosis is a term used to denote lipid accumulation within hepatocytes. "Another tumor suppressor, regulator of G protein signaling 6 (RGS6), is upregulated in the liver of NAFLD patients, forms a complex with ATM in the liver, promotes ATM phosphorylation, and drives hepatic steatosis." (PMID 37033223, 2023).
hyperlipidemia (1 paper, 2024). "RGS6 expression can be induced by several cytotoxic stimuli including alcohol, hyperlipidemia, and chemotherapeutics, an effect that may be achieved or amplified by down-regulation of miRNA-21." (PMID 38409136, 2024).
Insulin resistance (1 paper, 2023). Increased resistance towards insulin, that is, diminished effectiveness of insulin in reducing blood glucose levels. "Human patients with high hepatic RGS6 expression exhibited a correspondingly high inflammatory burden, pronounced insulin resistance and poor liver function." (PMID 38066447, 2023).
Intellectual disability (1 paper, 2025). "This includes the RGS6 gene, which was previously identified as 1 of 23 loci with pleiotropic effects on four or more human psychiatric disorders and associated with intellectual disability and other phenotypes related to neurodegeneration." (PMID 41374081, 2025).
night blindness (1 paper, 2022). Inability to see clearly in dim light. "Mutations in RGS6 may cause Hirschsprung’s disease 1, night blindness and congenital quiescence." (PMID 35309141, 2022).
pancreatitis (1 paper, 2019). Inflammation of the pancreas. "In a sub-analysis focusing on patients who were less than 10 years old, rs17179470 in RGS6 was strongly associated with pancreatitis." (PMID 35582721, 2019). "The authors also applied a targeted genotyping approach to test the reproducibility of the association of the ULK2 variant rs281366 and RGS6 variant rs17179470 with the risk of pancreatitis previously reported by the same group but the results were not significant." (PMID 35582721, 2019).
urothelial cell carcinoma (1 paper, 2016). "Here we demonstrate that RGS6 is robustly expressed in human urothelium, where urothelial cell carcinoma originates, and is downregulated in human UBC." (PMID 27713144, 2016).